GBA1LP (glucosylceramidase beta 1 like, pseudogene)
Synonyms: formerly GBAP; GBAP1
Gene: Transcribed unprocessed pseudogene on chromosome 1 (155,214,368 to 155,218,874, reverse strand). Ensembl gene ENSG00000160766.
Diseases named in the same sentence as GBA1LP in open-access papers:
GBA1LP is named in the same sentence as 1 disease in open-access papers, as found by Europe PMC text mining. Sharing a sentence is not in itself a finding about the gene and the disease.
GBA1LP shares sentences with these, for which no sentence is quoted: Gaucher disease (1 paper).